DNAAF5 (dynein axonemal assembly factor 5)
Description:
Cytoplasmic protein involved in the delivery of the dynein machinery to the motile cilium. It is required for the assembly of the axonemal dynein inner and outer arms, two structures attached to the peripheral outer doublet A microtubule of the axoneme, that play a crucial role in cilium motility.
Synonyms: HEATR2; FLJ20397; FLJ31671; FLJ39381; FLJ25564; CILD18
Tractability: PROTAC: ubiquitination databases record sites on it; its protein half-life has been measured.
Gene: Protein-coding gene on chromosome 7 (726,690 to 786,475, forward strand). Ensembl gene ENSG00000164818.
Subcellular location: Cytoplasm; Dynein axonemal particle
Subcellular location (Human Protein Atlas): Cytosol; Microtubules; Nucleoli
Gene Ontology:
Molecular function: dynein intermediate chain binding
Biological process: cilium movement; inner dynein arm assembly; outer dynein arm assembly
Cellular component: cytoplasm; cytosol; dynein axonemal particle; motile cilium
Genetic constraint (gnomAD): Loss-of-function variants: 64 observed, 70.36 expected, observed/expected ratio (o/e) 0.91, 90% interval 0.74 to 1.12. The synonymous counts are far from expectation, so gnomAD's model fits this gene poorly and the ratio says little. Missense variants: 1,253 observed, 1,057.9 expected, observed/expected ratio (o/e) 1.18, 90% interval 1.13 to 1.24. Synonymous variants: 655 observed, 498.19 expected, observed/expected ratio (o/e) 1.31, 90% interval 1.23 to 1.4.
Gene-disease validity (ClinGen):
ClinGen rates the evidence that DNAAF5 causes each of these diseases.
primary ciliary dyskinesia 18 (autosomal recessive): Definitive.
Homologues: Orthologues: macaque DNAAF5 (95% identical), guinea pig DNAAF5 (79% identical), mouse Dnaaf5 (78% identical), rat Dnaaf5 (77% identical), pig DNAAF5 (75% identical), dog DNAAF5 (75% identical), tropical clawed frog dnaaf5 (53% identical), Drosophila melanogaster Dnaaf5 (22% identical).
Diseases named in the same sentence as DNAAF5 in open-access papers:
DNAAF5 is named in the same sentence as 18 diseases in open-access papers, as found by Europe PMC text mining. Sharing a sentence is not in itself a finding about the gene and the disease. The quoted sentences say what the papers report.
primary ciliary dyskinesia (3 papers, 2022 to 2025). A rare, genetically heterogeneous, primarily respiratory disorder characterized by chronic upper and lower respiratory tract disease. "DNAAF5 is a dynein motor assembly factor associated with the autosomal heterogenic recessive condition of motile cilia, primary ciliary dyskinesia (PCD)." (PMID 37104040, 2023).
Hydrocephalus (2 papers, 2023 to 2024). Hydrocephalus is an active distension of the ventricular system of the brain resulting from inadequate passage of CSF from its point of production within the cerebral ventricles to its point of absorption into the systemic circulation. "None of the patients with PCD with variants in DNAAF5 in our cohort or patients with variants in DNAAF5 described by others showed clinical evidence of hydrocephalus, consistent with most human gene variants causative of PCD." (PMID 37104040, 2023).
male infertility (2 papers, 2021 to 2023). The inability of the male to effect fertilization of an ovum after a specified period of unprotected intercourse. "Only WT/MIS males produced live offspring, indicating that 2 missense alleles in Dnaaf5 cause male infertility." (PMID 37104040, 2023). "Five other dynein preassembly genes (DNAAF1, DNAAF3, DNAAF5, SPAG1, and CFAP298 (C21orf59)) are known to be associated with PCD and putatively, male infertility." (PMID 33635866, 2021).
colorectal cancer (1 paper, 2021). A primary or metastatic malignant neoplasm that affects the colon or rectum. "The subnetworks revealed genes that are previously reported as CRC-associated as well as several yet undeciphered genes that may contribute colorectal cancer, such as DNAAF5, RASL10B, DUSP19, and TTC27." (PMID 34790220, 2021).
hepatocellular carcinoma (1 paper, 2022). A malignant tumor that arises from hepatocytes. "This study revealed that the expression of DNAAF5 was increased in hepatocellular carcinoma and negatively correlated with the prognosis of patients." (PMID 36276075, 2022). "Then we overexpressed DNAAF5 in hepatocellular carcinoma tumor tissues, which correlates with poor patient survival outcomes." (PMID 36276075, 2022). "We investigated the role of DNAAF5 in hepatocellular carcinoma by using multiple groups of clinical tissues combined with data from the TCGA database." (PMID 36276075, 2022). "Furthermore, we constructed stable cell lines of HCC cells to confirm the cancer-promoting effects of DNAAF5 in hepatocellular carcinoma." (PMID 36276075, 2022). "Overall, DNAAF5 serves as a scaffold protein to recruit USP39 to form a ternary complex by directly binding the PFKL protein, thereby improving the stability of the latter, which promotes the malignant process of hepatocellular carcinoma." (PMID 36276075, 2022). "Dynein axonemal assembly factor 5 (DNAAF5) is the transcription factor of regulating the cytoskeleton and hydrodynamic protein complex assembly, however, it was not well elucidated in the malignant progression of hepatocellular carcinoma (HCC)." (PMID 36276075, 2022).
Joubert syndrome (1 paper, 2021). Joubert syndrome (JS) is characterized by congenital malformation of the brainstem and agenesis or hypoplasia of the cerebellar vermis leading to an abnormal respiratory pattern, nystagmus, hypotonia, ataxia, and delay in achieving motor milestones. "The remaining novel variants were: CCDC39:p.Glu598* (CADD, 37); CCDC40:c.1097delT (frameshift); CEP104:p.Glu698Lys (Joubert syndrome 25, Patient 9); DNAAF5:p.Val431Ala (Condel: 0.886); DNAH5 duplication of exon 1–48 (unknown significance); HYDIN:p.Pro3213Arg (likely pathogenic, Patients 17–18)." (PMID 34768622, 2021).
situs inversus (1 paper, 2023). A congenital condition in which there is complete right-to-left reversal of the position of the major thoracic and abdominal organs (that is, they are arranged in a mirror image of the normal positioning). "A total of 36% of situs inversus cases in our study were associated with the following genes: DNAH5, DNAI1, DNAI2, DNAAF5, and LRRC56." (PMID 37892347, 2023).
cancer (3 papers, 2015 to 2025). A tumor composed of atypical neoplastic, often pleomorphic cells that invade other tissues. "So far, we conjectured that DNAAF5 exerts its cancer-promoting effects by interacting with PFKL, which promotes the Warburg effect and accelerates the malignant processes of HCC." (PMID 36276075, 2022).
infection (1 paper, 2020). The state of being infected such as from the introduction of a foreign agent such as serum, vaccine, antigenic substance or organism. "At the same time, ciliary markers such as DNAH5, DNAAF5, MCIDAS, and CCNO were downregulated following infection of hNECs." (PMID 33409274, 2020).
tumor (1 paper, 2022). "In this study, we established that the highly expressed DNAAF5 proteins in HCC promote the malignant progression of tumor cells by increasing PFKL protein levels." (PMID 36276075, 2022). "However, tumor cell proliferation rates and colony formation were significantly decreased after DNAAF5 knockout, accompanied by an increase in sensitivity to sorafenib." (PMID 36276075, 2022). "In this study, we evaluated the mechanisms of DNAAF5 in HCC and found that DNAAF5 is generally highly expressed in tumor tissues of HCC patients, compared to their adjacent tissues." (PMID 36276075, 2022). "In addition, In vivo tumor formation assays showed that elevated levels of DNAAF5 promote HCC cell proliferation rates, and after USP39 knockdown in Hep3B-ov-DNAAF5 cells, the increased tumor volume due to increased expressions of DNAAF5 was significantly decreased." (PMID 36276075, 2022).
DNAAF5 also shares sentences with these, for which no sentence is quoted: ciliopathy (1 paper); endometriosis (1); lung disease (1); Neonatal respiratory distress (1); neuroblastoma (1); neurodegenerative disease (1); respiratory diseases (1); virus infection (1).